TLR4 (toll like receptor 4)
Diseases named in the same sentence as TLR4 in open-access papers (continued):
Sharing a sentence is not in itself a finding about the gene and the disease.
Stroke (continued). "In terms of inflammation, Engeletin showed stable binding to TLR4 (−8.6 kcal/mol) and NF-κB (−7.1 kcal/mol), forming salt bridges (e.g., ARG106D, ARG2305A) and hydrogen bonds, suggesting a potential role in attenuating stroke-related inflammation via the TLR4/NF-κB pathway." (PMID 41373604, 2025). "Since TLR4 mediates brain damage, screening for TLR4-blocking aptamers may be a useful strategy for the treatment of stroke." (PMID 40376266, 2025). "Multiple studies have demonstrated that the TLR4/NF-κB signaling pathway crucially facilitates the activation of neuroinflammation secondary to stroke, and there is evidence showing that inhibiting TLR4/NF-κB pathway activation can reduce cerebral edema and the infarct volume in rats with MCAO." (PMID 40004043, 2025). "Targeting platelet receptors dispensable for hemostasis, but guiding inflammation such as GPVI or key effector receptors of stroke-related inflammation such as TLR4, among others, are worth being pursued clinically based on robust preclinical efficacy and clinical safety data." (PMID 39582054, 2024). "Past investigations have underscored the pivotal role of TLR4 in mediating inflammatory responses of immune cells within the central nervous system, directly linking it to brain damage and neuronal death observed in cases of cerebral ischemia and stroke." (PMID 39070050, 2024). "We further revealed that transcription factor sp1 is able to regulate CIRP expression in ischemic neurons and CIRP may promote NETs formation in tMCAO mice via the TLR4/p38 signaling pathway, which may also provide insights into stroke treatment." (PMID 38377019, 2024). "Moreover, miR-15a/16–1 inhibition alleviates ischemic brain injury by suppressing IL-6, MCP-1, VCAM-1, and TNF-α, and miR-1906 application can ameliorate ischemic injury in experimental stroke by directly modulating the inflammatory initiator TLR4." (PMID 35906328, 2023). "In this context, ApTOLL, a Toll-like receptor 4 (TLR4) antagonist with proven neuroprotective effect in preclinical models of stroke and a very good pharmacokinetic and safety profile in healthy volunteers, is a promising first-in-class aptamer with the potential to address this huge unmet need." (PMID 36908619, 2023). "Reducing neuroinflammation by inhibiting the TLR4 pathway may be an effective strategy for improving cognitive impairment after stroke." (PMID 37397457, 2023). "Inhibition of TLR4 protects experimental stroke animals from injury." (PMID 36879557, 2023). "We found that ISO inhibited TLR4 signalling in diabetic model mice after stroke." (PMID 35419168, 2022). "The TLR4/MMP9-mediated reduction of astrocyte reactivity after ECS activation via CB2R is of special interest for stroke, as it has been suggested elsewhere that attenuation of the inflammatory process could be neuroprotective after tMCAO in rats." (PMID 35721207, 2022). "Increased TLR4 expression correlates with increased stroke severity." (PMID 34711943, 2022). "The observed elevated expression of toll-like receptor 4 on peripheral blood monocytes of stroke patients aggravated stroke and inflammatory lesions, and the same monocytes were also involved in systemic inflammation following stroke." (PMID 36275012, 2022). "Importantly, we have also found that NETs exert a deleterious effect in the acute phase of stroke in a platelet-TLR4 dependent manner and, subsequently, that its pharmacological modulation has a neuroprotective effect." (PMID 35250974, 2022). "In TLR4 knockdown stroke animal models, the infarct sizes were significantly decreased." (PMID 35966335, 2022). "Additionally, TLR4 is also responsible for chronic neuroinflammation leading to brain damage after stroke, as it induces the production and release of TNF-α, IL-6, and NO, causing neuronal cell death." (PMID 35283778, 2022).
Stroke (continued). "The primary objective of this study aims to investigate short-term add-on efficacy and mechanism of Panax notoginseng (Sanqi) for aspirin resistance in secondary stroke prevention via TLR4/MyD88/NF-κB signaling pathway with a more strictly randomized controlled trial (RCT)." (PMID 36550905, 2022). "Taken together, these findings support a pro-inflammatory role of the neutrophil TLR4 receptor, and suggest that specifically targeting TLR4 in neutrophils may offer a novel therapeutic approach for stroke." (PMID 34745132, 2021). "Indeed, anti-TLR4-antibody effectively treated stroke in vivo, hinting the therapeutic potency of anti-TLR4-antibody." (PMID 34071605, 2021). "In TLR4 knockout mice, smaller stroke sizes and better neurocognitive functions are observed." (PMID 34829993, 2021). "Also, Toll-like receptor (TLR)-4 has been ascribed an aggravating function in inflammation after stroke and myocardial infarction resulting in the development of heart failure." (PMID 34992548, 2021). "In addition, microglia enhance astrocytes responses via Toll-like receptor 4 (TLR4) activation under insults, injury, or inflammation in stroke." (PMID 34305569, 2021). "TLR4 antagonists TAK242 reduce these deleterious effects of stroke TLR4 signal transduction." (PMID 34956584, 2021). "Furthermore, TLR4 has been identified to be involved in regulating NSCs during stroke progression, but the correlation of TLR4 with circTTC3 and miR-372-3p remains elusive." (PMID 33579365, 2021). "Recently, it has been demonstrated that the absence of TLR4 in a mouse model of stroke polarizes the cells toward an N2 phenotype associated with neuroprotection." (PMID 34447377, 2021). "Activation of the TLR3/TRIF pathway could down-regulate the levels of TLR4/MyD88, reducing microglial activation and the expression of inflammatory factors to reverse the adverse effects of TLR4 on post-stroke injury." (PMID 34276530, 2021). "CircTTC3, miR-372-3p, and TLR4 may serve as potential targets for the treatment of CIR injury during stroke." (PMID 33579365, 2021). "In conclusion, casticin improved the neurological functions of MCAO rats via inhibiting the TLR4/NF‐κB pathway and might have the potential to be developed into a neuroprotective agent for stroke patients." (PMID 33704926, 2021). "TLR4 and TLR2 are pattern recognition receptors that can be sensed by immune innate cells and activate downstream signaling inflammatory cascade, which are the most investigated receptors associated with stroke-induced inflammation response." (PMID 35185744, 2021). "In addition, studies have found that the number of TLR4‐single cells in peripheral blood increased significantly in patients with cerebral ischemia, and the expression of TLR4 was closely related to the degree of inflammation detected after stroke." (PMID 33704926, 2021). "TLR4 (toll-like receptor 4) plays a key role in the immune response elicited after stroke." (PMID 34745132, 2021). "Endothelium‐specific TLR4 activation was shown to be a critical mediator of stroke." (PMID 34042301, 2021). "This study focused on whether TLR4-mediated neuro-inflammation is involved in central pain after stroke." (PMID 34643849, 2021). "Among the TLR isotypes, TLR2, and TLR4 are crucial inflammatory mediators after stroke." (PMID 32174916, 2020). "In summary, our study confirmed that basal rat plasma exosomes attenuated the ischemic-induced inflammatory response, neuronal apoptosis, and inflammasome-dependent pyroptosis after stroke in rats and that melatonin significantly enhanced the therapeutic effect by regulating the TLR4/NF-κB pathway." (PMID 33013286, 2020). "TLR4 paradoxically promotes neuroblast migration and neurogenesis after stroke." (PMID 32174916, 2020). "Our results show that TLR4 expression, and downstream signaling activation, occur robustly in penumbral astrocytes during acute focal cerebral ischemia at 48 hrs and during the chronic phase of stroke, up to 7 days after transient MCAO." (PMID 32148958, 2020).
Stroke (continued). "Furthermore, it was found that the SSa treatment (0.01%) significantly decreased the expression of TLR4 and nucleus NF-κB 4 days after stroke." (PMID 33335763, 2020). "TLR-4 knockout mice have lower infarct size in stroke model compared to wild type, suggesting that antagonizing TLR-4 may have a role in neuroprotection." (PMID 33659224, 2020). "Some research also found a significant rise in TLR2 and TLR4 on peripheral monocyte after stroke." (PMID 31134076, 2019). "In this case, several polyphenols have been shown to significantly attenuate Aβ-plaques and inflammatory cytokine and chemokine production via intervening different signaling pathways, explicitly targeting the TLR4/NF-κB-signaling pathway in AD, PD, MS, or stroke." (PMID 31134076, 2019). "LRRK2, CALM1, CXCR4, TLR4, CTNNB1, and CXCR2 may be implicated in AF and the hub-genes of CD19, FGF9, SOX9, GNGT1, and NOG may be associated with stroke." (PMID 30760287, 2019). "Likewise, other groups also found reduced focal lesions in Tlr4−/− mice not only after experimental stroke but also after experimental TBI." (PMID 28912751, 2017). "Since NF-κB is a crucial modulator of inflammations during cerebral I/R injury, the organism of rats suffering from stroke could down-regulate inflammation and alleviate cerebral I/R injury by suppressing TLR4/NF-κB signaling pathway." (PMID 29383171, 2017). "However, it still remains to be evaluated if perturbation of the ischemic neuroinflammation by TLR4 inhibition on both the innate and adaptive immune response levels also influences the long-term prognosis after stroke." (PMID 26849209, 2016). "We therefore investigated whether TLR4 inhibition could be used to treat stroke in a standard model of focal cerebral ischemia." (PMID 26849209, 2016). "In contrast to CB2R, the upregulation of IBA1 and TLR4 was less prominent after stroke." (PMID 26186541, 2015). "A similar pattern of TLR4 mRNA expression was found after stroke." (PMID 26186541, 2015). "Our previous results showed that the number of TLR4+ monocytes in the peripheral blood of patients with cerebral infarction was significantly increased, and the correlation analysis showed that TLR4 expression and cytokine levels were closely related to stroke severity." (PMID 25928750, 2015). "Our findings also imply that inhibiting microglial activation via TLR4 may be a new avenue of therapy for stroke treatment." (PMID 26086415, 2015). "For example, TLR4-deficient mice do not show increased inflammatory responses compared to wild-type mice post-stroke." (PMID 26597908, 2015). "Moreover, it was found that the level of TLR4 mRNA elevated significantly within peripheral blood in patients with transient ischemic attack (TIA) or stroke when compared with that in the patient with asymptomatic internal carotid artery stenosis." (PMID 23864765, 2013). "Although stimulation of TLRs in microglia activates functions that are important for the elimination of pathogens, microglial TLRs, particularly TLR2 and TLR4, mediate stroke-induced injury to the CNS, neuroinflammation, and neuronal damage by responding to endogenous compounds." (PMID 23589665, 2013). "Therefore, we hypothesized that the TLR4/MyD88/NF-κB pathway might be the critical pathway through which Evobrutinib inhibits the pro-inflammatory polarization of microglia following stroke." (PMID 40263985, 2025). "In stroke patients, gut microbiota dysbiosis is often characterized by an increased abundance of pro-inflammatory bacteria, such as Prevotella and Enterobacteriaceae, which can activate the Toll-like receptor 4 (TLR4) and nuclear factor kappa B (NF-κB) signaling pathways." (PMID 40919209, 2025). "In addition, TEAS can inhibit the TLR4/MyD88/NF-κB pathway, reduce ischemic brain damage after stroke, inhibit inflammation, cell death, and microglia activation, improve the motor neurons in spinal cord downlink control function, and reduce excessive muscle tone." (PMID 39665041, 2024).
Stroke (continued). "Similarly, a recent study has shown that TLR4 regulates neutrophils dynamics in stroke." (PMID 36091114, 2022). "Additionally, TLR4 inhibition improves neurological function after stroke in diabetic rats." (PMID 35419168, 2022). "As a result, TLR2 and TLR4 might be regarded as potential stroke therapeutic targets." (PMID 35510663, 2022). "Indeed, TLR4 mediated action in astrocytes may contribute to HMGB1 action on the brain in experimental rat stroke models." (PMID 34208101, 2021). "Therefore, therapeutic strategy targeting at HMGB-1/TLR4/NF-κB signaling may be a promising method to limit neuroinflammatory processes and alleviate stroke damage." (PMID 33335763, 2020). "Therefore, targeting TLR4 is a potential therapeutic option against neuroinflammation after stroke." (PMID 33552066, 2020). "Also, TLR-4 was proposed as an important therapeutic target for stroke-induced neuroinflammation." (PMID 29849502, 2018). "A study showed that the activation of the Gal-3-dependent TLR-4 pathway may contribute to sustained microglial cell activation, prolonging the inflammatory response in a murine neuroinflammatory model (LPS injection) and in patients with stroke." (PMID 30060489, 2018). "Thus, TLR4 inhibition represents an attractive potential therapeutic option for stroke treatment." (PMID 26849209, 2016). "Thus, inhibiting the activation of microglial activation via TLR4 may be a new avenue for stroke treatment." (PMID 26086415, 2015). "In the present study, we hypothesize that exposure to PCB153 assembled onto nanoparticles contributes to the development of stroke by disruption of the integrity of the cerebral endothelium and induction of proinflammatory responses through stimulation of TLR4 signaling." (PMID 23690990, 2013). "Therefore, stroke-induced TLR4 signaling may be blocked completely, leading to reduced injury, and stroke-induced TLR4 signaling would shift from NF-κB induction to IRF3 induction." (PMID 21982558, 2011). "After stroke, the injured brain releases large amounts of HMGB1, which activates the RAGE and TLR4 pathways, transmitting danger signals to surrounding tissues." (PMID 41050264, 2025). "Melatonin and the neuropeptide PNX-14 inhibited microglia activation-mediated inflammation after stroke by suppressing the high expression and release of HMGB1 and modulating the subsequent activation of the TLR4/MyD88/NF-κB signaling pathway." (PMID 38740617, 2025). "Although there are multiple receptors for HMGB1, post-stroke HMGB1 receptor studies have centered around Toll-like receptors (TLR-2 and TLR-4) and the receptor for advanced glycosylation end products (RAGE)." (PMID 38740617, 2025). "Myeloid Differentiation Factor 2 (MD2), an accessory protein of Toll-like receptor 4 (TLR4), has emerged as a key player in mediating inflammatory responses in stroke." (PMID 40723833, 2025). "Consistent with another experimental model of stroke, the evidence demonstrated that HMGB1-mediated TLR4 activation is necessary to maintain NSC proliferation and promote cell differentiation into neuroblasts, promoting their migration." (PMID 38891900, 2024). "Another study has also revealed that fecal transplants of mice from patients with cognitive impairment after stroke showed worse cognitive function, higher levels of LBP and gut toll-like receptor 4, and more severe gut disruption." (PMID 37113132, 2023). "Increased levels of miR-1906, a new regulator of toll-like receptor 4 (TLR4) signaling, were found in MSC EVs after treatment with lithium, which led to reduced cerebral inflammation and rapid neuroprotection in mice with stroke." (PMID 36361805, 2022). "In animal models of stroke, extracellular HMGB1 has been found to stimulate inflammation, albeit through TLR4 signaling instead of TLR2, as we showed here." (PMID 35573828, 2022).
Stroke (continued). "To further explore the in vivo mechanism of NETs formation and, considering that platelet TLR4 plays an instrumental role in platelet-rich thrombosis mediated by NETosis, we hypothesized that TLR4 on thrombocytes might have a role in NETs formation in experimental stroke by pMCAO." (PMID 35250974, 2022). "Evidence also indicates that TLR4 is involved in promoting NSC differentiation into astrocytes and neurons during stroke progression." (PMID 36671403, 2022). "Upon stroke, reports have shown that CD14 receptors and TLR4 are robustly expressed in activated microglia in the infarct brain zone, enabling microglial activation." (PMID 35986375, 2022). "Prdx-1, Prdx-2, Prdx-5, and Prdx-6 are secreted by necrotic cells in the brain early after stroke inducing the release of pro-inflammatory cytokines, which are then recognized by TLR2 and TLR4." (PMID 34208834, 2021). "Thus, targeted inhibition of TLR4 could reduce microglial activation and release of pro-inflammatory factors, coordinate the M1/M2 polarization of microglia, and play a protective role in stroke-induced brain injury." (PMID 34276530, 2021). "Of note, a cell-specific approach may reduce adverse effects that could occur after TLR4 antagonist administration such as reduced neuronal survival and proliferation or the inhibition of phagocytosis by microglia, which is of extreme relevance in stroke pathology." (PMID 34745132, 2021). "Extracellular Prx1 is an endogenous ligand of TLR4, which has been shown to be upregulated and detected around TUNEL-positive cells in mouse models of stroke." (PMID 34162400, 2021). "In the ischemic brain, DJ-1 is released into the extracellular space from necrotic neurons within 24 h after stroke onset and makes direct contact with TLR2 and TLR4 in infiltrating myeloid cells." (PMID 34014921, 2021). "The current study suggests that both LTA (TLR2) as well as LPS (TLR4) pathways are activated in SVO stroke and likely contribute to inflammation either before and/or after the SVO strokes." (PMID 33753837, 2021). "There were three- and fivefold increases in expression of TLR2 and TLR4 in the DCAL and MCAo models respectively and DCAL stroke had the highest expression of TLR4 within the models." (PMID 33097782, 2020). "Type 1 IFN-stimulated genes reaction in the microglia exposed to ischemia/reperfusion depends on innate immune receptors including TLR4 and IFNAR1, which played a deleterious role in the outcome after stroke." (PMID 32746852, 2020). "In experimental animals as well as in stroke patients, it has been shown that HMGB1, a DAMP protein and also a ligand of TLR2 and TLR4, is increased in serum." (PMID 31134076, 2019). "After a stroke, DAMPs activate TLR2 and TLR4 in microglia to increase the production of pro-inflammatory cytokines." (PMID 30809253, 2018). "Nonetheless, in a separate study, secreted galectin-3 was shown to act as a ligand for the toll-like receptor 4 (TLR4) and promote inflammatory response in a murine neuroinflammatory LPS model and in the brain of stroke patients." (PMID 29867350, 2018). "The modulation of TLR4/Prx6 pathway by MLC901 seems to represent a key step in these anti-inflammatory effects and to contribute to its protective effects against stroke." (PMID 30584250, 2018). "In cerebral ischemia/reperfusion models for stroke injury, HSP70 binds to TLR4, activating MyD88-IRAK-TRAF6 and NF-κB pathways, with downstream induction of TNFα and other cytokines, as observed for nPM-LPS responses." (PMID 28410596, 2017). "D-4F treatment significantly (n=8/group, *p<0.05) decreases TLR4, MMP9 and nuclear NFκB expression compared to PBS treated T1DM stroke control rats at 48 hours after stroke." (PMID 29221142, 2017). "Consistently, our comparative study of Danshensu and HSYA in the neuroprotection against stroke among single and combination groups suggest that Danshensu and HSYA in combination produced the most effective inhibitory effects on TLR4 and NF-κB expressions." (PMID 29383171, 2017).